RHOA (ras homolog family member A)
Diseases named in the same sentence as RHOA in open-access papers (continued):
Sharing a sentence is not in itself a finding about the gene and the disease.
colon carcinoma (continued). "Notably, it was found that co-transfection with the TSB, but not the TSB control, reversed miR-340-5p mimic-induced inhibition of and total RhoA and Rho-GTP activity in colon cancer cells." (PMID 33037251, 2020). "In the treatment of colon cancer, NOB negatively affects RhoA expression." (PMID 32380783, 2020). "miR-223 upregulation in a colon cancer cell line upregulated c-Myc, cyclinD1, MMP7, and vimentin expression, downregulated E-cadherin, increased nuclear expression of β-catenin, and enhanced RhoA activation." (PMID 28969027, 2017). "Such context-dependent translation of some miRNAs targets is supported by our findings showing that knocking down miR-155-5p in non-serum starved colon cancer cells triggered increased expression of RhoA mRNA." (PMID 28146427, 2017). "Consistent with the findings of colon cancer tissue microarray, we also found that miR-126 significantly suppressed the expression of CXCR4, the activity of RhoA, and the expression of RhoGEF, ROCK, PI3K, PAK, PKN and up-regulated the expression of ARHGAP5 in colon cancer cells." (PMID 27517626, 2016). "MiR-126 negatively correlated with CXCR4, RhoA, RhoGEF and ROCK in human colon cancer." (PMID 27517626, 2016). "Moreover, it was shown that cyclin A2 negatively controls cell motility by promoting RhoA-ROCK activation through a direct interaction with RhoA in breast and colon cancer cells." (PMID 26418031, 2015). "Similarly, over expression of RhoA, Rac1, and Cdc42 all led to induced COX-2 expression in NIH3T3 cells, MDCK epithelial cells, and HT29 colon cancer cells through a NF-κB dependent mechanism." (PMID 26416248, 2015). "In conclusion, we first reported that FZD7 may be important in the survival, invasion and metastatic capabilities of colon cancer cells, at least partly, through expression of c-Jun, phosphorylation of c-Jun and JNK, and activation of RhoA." (PMID 19773752, 2009). "Interestingly, it was found that co-incubation with this specific blocker dose-dependently reversed mimic miR-340-5p-induced inhibition of RhoA mRNA expression, indicating that this specific region of 3 ́-UTR of RhoA mRNA is a functional target of miR-340-5p in colon cancer cells." (PMID 33037251, 2020). "In addition, either in miR-126-overexpressing or in miR- 126-silenced colon cancer cells, the restoration of CXCR4 could significantly reverse the proliferation and invasion, as well as abolish the effects of miR-126 on RhoA signaling pathway." (PMID 27517626, 2016). "Even though RhoA may be involved in colon cancer progression, our data reveal that RhoA is not suppressed by AZA197 treatment and thus is not a target for AZA197." (PMID 24279335, 2013). "Finally, one of the main findings in our study is that ROCK, but not RhoA, activity is related to invasiveness in our collection of colon cancer cell lines." (PMID 23144867, 2012). "The finding that RhoA activity was not related with the invasiveness of the different colon cancer cell lines is not in agreement with the frequent involvement of the RhoA pathway in tumour cell invasion, particularly through the activation of its effector kinase ROCK." (PMID 23144867, 2012). "Therefore, we hypothesized that CUR reactivated the ARHGEF12 TSG to block colon cancer cell proliferation and migration via cancer pathways, whereas CUR might exert an inhibitory effect on invasion and migration by blocking the binding of ARHGEF12 to RhoA." (PMID 37731740, 2023). "Moreover, RhoA mRNA expression was found to be higher in serum-grown compared to serum-free, suggesting a negative correlation between miR-340-5p and RhoA mRNA in colon cancer cells." (PMID 33037251, 2020). "In addition, either in miR-126-overexpressing or in miR-126-silenced colon cancer cells, the restoration of CXCR4 could significantly reverse miR-126-induced suppression of colon cancer cell migration, invasion and proliferation, as well as abolish the effects of miR-126 on RhoA signaling." (PMID 27517626, 2016).
colon carcinoma (continued). "In SW620 and HT-29 human colon cancer cells, AZA197 demonstrated selectivity for Cdc42 without inhibition of Rac1 or RhoA GTPases from the same family." (PMID 24279335, 2013).
Hypertension (83 papers, 2011 to 2025). The presence of chronic increased pressure in the systemic arterial system. "RhoA/Rho kinase signaling has long been implicated in hypertension due to its important role in smooth muscle contraction." (PMID 36902363, 2023). "This gene pair has been linked to hypertension, providing further evidence of S1P (sphingosine 1-phosphate) and RhoA signaling involvement." (PMID 38137595, 2023). "ARHGEF15 encodes a specific guanine nucleotide exchange factor for the activation of Ras homolog family member A (RhoA), a GTPase, which has been linked to higher blood pressure and hypertension over the Rho/ROCK signaling cascade." (PMID 35523767, 2022). "In VSMCs, Ang II induces JAK2, which activates RhoA guanine nucleotide exchange factor I, Arhgef1, which eventually activates RhoA signaling and causes hypertension." (PMID 36324691, 2022). "Ang II-induced hypertension requires Rho activation, and enhanced sensitivity to Ang II via the Wnt-RhoA pathway in aged vasculature contributes to aging-associated salt-sensitive hypertension." (PMID 33803946, 2021). "A number of mechanisms implicated that RhoA/ROCK hyperactivation in hypertension includes the dysregulation of Rho GEFs." (PMID 33803946, 2021). "Third, our prior analysis that RHOA, a member of the actin cytoskeleton pathway and associated with hypertension etiology in endothelial and vascular smooth muscle cells, was differentially expressed in PBMCs between AA and white hypertensive women." (PMID 32443852, 2020). "In VSMCs, stimulation of JAK2 by Ang II leads to activation of RhoA guanine nucleotide exchange factor I, Arhgef1, which, in turn, stimulates RhoA signaling, causing hypertension." (PMID 31703282, 2019). "Several studies implicated abnormal RhoA/Rho kinase pathway in the pathophysiology of hypertension associated with diabetes." (PMID 28678840, 2017). "The underlying mechanism for the enhanced RhoA/ROCK signaling in hypertension was shown to be a consequence of the upregulated renin-angiotensin-aldosterone system, and an increased production of reactive oxygen species." (PMID 26635606, 2015). "Furthermore, we simulated the tumor microenvironment for in vivo experiments and discovered that the RhoA/ROCK signaling pathway is also implicated in apatinib-induced hypertension and vascular remodeling mechanisms in mice with gastric cancer." (PMID 39850566, 2024). "Indeed, others have found that VSMC contractile abnormalities are enough to cause systemic hypertension including myosin phosphatase and RhoA/Rho kinase." (PMID 34755572, 2021). "While there have been few studies directly investigating the role of the actin cytoskeleton structure in these cells as a causative mechanism of hypertension, several members of this pathway, including RHOA and ROCK, have identified roles in T and other immune cell cytoskeletal structure." (PMID 32443852, 2020). "Excessive calorie intake and low physical activity cause hypertension, obesity and insulin resistance, all of which cause endothelial dysfunction associated with down-regulation of eNOS/NO pathway and up-regulation of RhoA/Rho-kinase pathway, forming a vicious circle of metabolic disorders." (PMID 25365359, 2014). "In addition to the presented MLN4924-induced RhoA overactivation in cancer cell lines, Mdmx may be involved in conditions such as hypertension or decreased brain size due to Cul3 mutations where RhoA is also found to be overactivated." (PMID 39404389, 2024). "RhoA activation then induces RhoA-dependent stress fiber formation and enhances cell-substratum adhesion, which reduces endothelial-cell motility and angiogenesis, and causes various cardiovascular disorders such as hypertension, atherosclerosis, diabetes, and hypercholesterolemia." (PMID 33803946, 2021).
Hypertension (continued). "For example, RhoA expression is increased in aging vessels, and klotho deficiency and high salt intake trigger noncanonical Wnt-Rho activation; klotho replacement therapy, Wnt inhibitors, and Rho-kinase inhibitors are expected to be new therapies in aging-associated hypertension." (PMID 33803946, 2021). "RhoA activation contributes to vascular constriction and hypertension, and CUL3Δ9-associated ubiquitin ligase activity toward RhoA is impaired, suggesting that CUL3Δ9 mutations may act dominantly by sequestering substrate adaptors and disrupting CUL3WT complexes." (PMID 28804198, 2017). "In cardiovascular diseases including hypertension, RhoGEFs and RhoGAPs are believed to be key molecules involved in the hyperactivation of RhoA." (PMID 40943595, 2025). "As such, targeting RhoA/ROCK activity has been a conceptually appealing therapeutic strategy for hypertension and other CVDs." (PMID 40777343, 2025). "Supporting this, rat models of apatinib-induced hypertension exhibit upregulation of RhoA and ROCK2 in the mid-aorta, accompanied by reduced MLCP activity and increased ET-1 and collagen I expression." (PMID 41301525, 2025). "In cardiovascular diseases, RhoGEFs such as ARHGEF1 and LARG contribute to hypertension and aneurysm formation through activation of the Ang II‐induced RhoA/ROCK pathway, leading to endothelial dysfunction." (PMID 41020039, 2025). "Overactivation of the RhoA/ROCK pathway has been reported to be involved in the etiology of hypertension." (PMID 40165590, 2025). "As such, RhoA/ROCK hyperactivity and increased pMLC have been identified as major contributors to age-associated vasoconstriction and hypertension." (PMID 40777343, 2025). "This was accompanied by enhanced NADPH oxidase activity and superoxide production, all of which were normalized by the ROCK inhibitor fasudil, highlighting the role of RhoA/ROCK in early vascular remodeling even before the onset of hypertension." (PMID 41301525, 2025). "Future research on RhoA/ROCK inhibitors in hypertension focus on improving therapeutic precision, identifying specific disease mechanisms, and optimizing clinical use." (PMID 41301525, 2025). "In this analysis, several proteins associated with the RhoA/Rho kinase pathway showed changes consistent with hypertension and cerebral perfusion dysregulation, suggesting that the RhoA/Rho kinase pathway is an important target for age‐dependent hypertension." (PMID 38568071, 2024). "Previously, our team’s study has demonstrated that apatinib can induce hypertension in WKY rat models through the activation of the RhoA/ROCK pathway, specifically via Rho protein kinase (ROCK)." (PMID 39850566, 2024). "The RhoA/ROCK pathway is involved in the pathogenesis of hypertension and mediates smooth muscle contraction, eNOS inhibition, endothelial dysfunction and vascular remodeling." (PMID 35811723, 2022). "The RhoA/ROCK signaling pathway is deeply involved in arterial hypertension, cardiovascular–renal remodeling, hypertensive nephropathy and posttransplant hypertension." (PMID 35811723, 2022). "In our study, echocardiography revealed that apatinib induced hypertension through the RhoA/ROCK pathway and eventually led to left ventricular hypertrophy, consistent with previous studies." (PMID 35811723, 2022). "This means that apatinib enhances the activation of the RhoA/ROCK signaling pathway in the tumor environment, causing hypertension." (PMID 35811723, 2022). "Previous works have reported that PECAM-1 is an important feature of differentiated VSMCs, whereas the hypercontractility phenotype of differentiated VSMCs usually seen in diabetes and hypertension was correlated with RhoA upregulation." (PMID 36292250, 2022). "Exposure to IH activated RhoA/Rho-kinase in the aorta and mesenteric arteries of animal models, which is required for IH-induced arterial remodeling, and hypertension." (PMID 34504429, 2021).
Hypertension (continued). "Only Wnt inhibitor LGK974 suppressed vascular RhoA activation and vasoconstriction in these high-salt-fed mice, preventing the development of hypertension, and Rho inhibitor fasudil showed a similar effect to that of LGK974." (PMID 33803946, 2021). "A study using aortae from mice expressing a hypertension-inducing PPARγ P457L mutant reports a reduction in neddylated, active Cullin3, along with an elevation of total RhoA protein and ROCK activity." (PMID 34136490, 2021). "A number of studies analyzing data from in vitro and ex vivo experiments have shown that RhoA-activity is increased in VSMCs in different models of hypertension." (PMID 33906663, 2021). "Our findings of increased aortic pulse wave velocity and reduced resistance vessel distensibility now identify that the established RhoA hyperactivation in MLK3-KO mouse arterioles is associated with increased vascular stiffness and hypertension." (PMID 34324442, 2021). "The activation of the RhoA/ROCK pathway plays a pivotal role in the pathogenesis of hypertension and cardiovascular-renal diseases through interaction with Ang II, oxidative stress, and nitric oxide (NO)." (PMID 33803946, 2021). "Experimental models of hypertension exhibiting vascular RhoA/ROCK activation are augmented with a high-salt diet." (PMID 33803946, 2021). "As before introduced, numerous experimental animal models have been developed for understanding the physiological and pathophysiological role of Ca2+ sensitization in VSM contraction in normal BP and/or hypertension through RhoA/ROCK or PKC/CPI-17 signaling." (PMID 34357074, 2021). "In this context, RhoA has been suggested as a therapeutic target in hypertension with positive effects also on cardiac hypertrophy." (PMID 33906663, 2021). "It has been demonstrated that hypertension-causing mutations in CUL3 impair RhoA ubiquitylation and that selective expression of mutant CUL3 in VSMCs results in augmented RhoA signaling and vascular dysfunction, leading to elevation of BP." (PMID 32731518, 2020). "Arhgef1 plays a significant role in Ang II/AT1 receptor-induced RhoA activation in smooth muscle cells, vasoconstriction, and hypertension, and Arhgef1/RhoA signaling is turned on by renin-angiotensin-aldosterone-system (RAAS) activation in humans." (PMID 31174369, 2019). "Although many systemic, neural, paracrine, and autoregulatory mechanisms contribute to afferent arteriolar dynamics, in AngII-dependent hypertension a direct effect was observed between the RhoA/ROCK pathway and the endogenous production of AngII." (PMID 31500276, 2019). "Experimental models of hypertension exhibit increased vascular RhoA/ROCK activation, processes that are augmented with high salt diet." (PMID 29394331, 2018). "This confirms that basal RhoA/Rho kinase-dependent calcium sensitization (recorded in the absence of endogenous pressor systems) was attenuated in spontaneous hypertension but it was enhanced in salt hypertension." (PMID 28197417, 2017). "It is rather difficult to describe the exact role of RhoA/Rho kinase-dependent calcium sensitization in hypertension." (PMID 28197417, 2017). "In conclusion, the studies with acute Rho kinase inhibition suggested the enhanced participation of RhoA/Rho kinase pathway in the maintenance of increased systemic resistance and elevated blood pressure in both experimental and human hypertension." (PMID 28197417, 2017). "Increased activity of the RhoA/ROCK pathway is observed in experimental hypertension models and hypertensive patients." (PMID 26635606, 2015). "Different signaling pathways are involved in hypertension-induced vascular remodeling such as the RhoA/ROCK pathway which results in an increased in actin polymerization and depletion in G-actin." (PMID 26557089, 2015).
Hypertension (continued). "Another aspect related to PVAT addressed in this study was activation of the RhoA/Rho-kinase pathway, a key modulator of vascular smooth muscle contraction and contributor to the pathophysiology of arterial hypertension." (PMID 24490784, 2014). "Additional investigations implicating the RhoA/ROCK pathway in the pathogenesis of hypertension, coronary vasospasm, stroke, atherosclerosis, heart failure, and diabetes indicate its potential role as an important therapeutic target." (PMID 24710574, 2014). "Clearly, further studies are needed to confirm the role of TCTP-mediated RhoA regulation in the development of hypertension." (PMID 24918292, 2014). "Mounting evidence suggests a role for RhoA/Rho kinase signaling in the increased muscle contractility in the development of hypertension in humans." (PMID 24918292, 2014). "Increased activation of ras homolog gene family, member A (RhoA)/Rho-kinase signaling has been postulated to mediate hypertension in mice subchronically exposed to ambient PM." (PMID 20980218, 2011). "This highlights Arhgef11 as an upstream regulator of the RhoA/ROCK pathway in hypertension." (PMID 41301525, 2025). "Moreover, RhoA/ROCK pathways in vascular smooth muscles plays an important role in the pathogenesis of hypertension, coronary artery spasm and contributes to angina, myocardial infarction, and sudden death." (PMID 40943595, 2025). "Likewise, RvD1 reduced Ang II-induced hypertension and vascular remodeling in vascular smooth muscle cells through suppression of the RhoA/MAPK pathway, including reduction in ERK phosphorylation." (PMID 41463049, 2025). "In addition, RHOA was associated with chronic hypoxic foetal and adult sheep, suggesting an important role of RhoA pathways in hypertension control in newborns." (PMID 38773423, 2024). "Also, the inhibition of RhoA activation reduced the angiotensin II-dependent hypertension development." (PMID 37197584, 2023). "By activating the non-canonical Wnt5a/RhoA pathway, Klotho deficiency increases salt sensitivity in patients with hypertension which leads to increased total peripheral resistance via vasoconstriction, therefore raising BP." (PMID 36457804, 2022). "Also the beneficial effects of ExT on high blood pressure and cardiac damage were abolished by inhibition of RhoA/ROCK signal pathway and induced by activation of RhoA/ROCK signal pathway in SHR." (PMID 36284153, 2022). "We may speculate that this increased cofilin-1 expression could be a compensatory mechanism against aortic stiffening in SHRc, induced by high activity of the RhoA/Rho-kinase pathway, observed in hypertension." (PMID 33679438, 2021). "Thus, salt intake and increased salt sensitivity are associated with the development of hypertension, increasing ADMA production, decreasing NO production, and promoting RhoA activation." (PMID 33803946, 2021). "The review of genetic targeting of RhoA signaling on hypertension is recommended." (PMID 34357074, 2021). "Furthermore, RhoA/ROCK-activation in VSMCs has been shown to play an important role in hypertension." (PMID 33906663, 2021). "Interestingly, the activity of the RhoA/ROCK pathway has been widely investigated in the pathogenesis of hypertension." (PMID 31500276, 2019). "RhoA/Rho-kinase and NO regulation contribute to IL-17A-mediated hypertension." (PMID 31572188, 2019). "Thus, Fasudil attenuates soluble fms-like tyrosine kinase-1 (sFlt-1)-induced hypertension in pregnant mice through RhoA/ROCK pathway, which would become a potential strategy for PE therapy." (PMID 29262624, 2017). "Increased activity of RhoA/ROCK pathway has been observed in experimental hypertension models and hypertensive patients, which appear to be the consequence of the up-regulation of renin-angiotensin-aldosterone system and the increased production of reactive oxygen species (ROS)." (PMID 29262624, 2017).